EPHA4 (EPH receptor A4)
Diseases named in the same sentence as EPHA4 in open-access papers (continued):
Sharing a sentence is not in itself a finding about the gene and the disease.
Cerebral ischemia (2 papers, 2023 to 2025). Restriction of arterial blood supply to the brain associated with insufficient oxygenation to support the metabolic requirements of the tissue. "Conditional knockdown of EphA4 in OPCs enhances remyelination after cerebral ischemia." (PMID 40518508, 2025). "Therefore, we believe it is needed to elucidate the potential mechanisms by which neuronal EphA4 influence outcome of cerebral ischemia." (PMID 37519758, 2023).
cognitive decline (2 papers, 2014). "EphA4/c-Abl signaling could hence be a relevant pathway involved in the early cognitive decline observed in AD patients." (PMID 25027113, 2014).
cutaneous melanoma (2 papers, 2021 to 2025). A primary melanoma arising from atypical melanocytes in the skin. "EphA4 is mutated in approximately 4% of the 1499 skin melanoma patients for which data are available in cBioPortal (cbioportal.org)." (PMID 34139238, 2021). "Analysis of the TCGA collection of skin cutaneous melanoma samples revealed that high EphA4 mRNA expression correlates with decreased patient survival in tumors that also exhibit high expression of one or more of the five ephrinA ligands, which bind EphA4 with high affinity." (PMID 34139238, 2021).
dementia (2 papers, 2014 to 2025). Loss of intellectual abilities interfering with an individual's social and occupational functions. "Tau may be involved in synaptic dysfunction in dementia, strengthening the association with EphA4." (PMID 25027113, 2014). "Top proteins with high feature importance in the clinical impairment signature again highlighted ACHE and NPTXR as well as additional targets linked to neuroplasticity (EPHA4 and CNTFR) and immune activation (MSMP and KLK3), underscoring their potential for transdiagnostic dementia staging." (PMID 40665048, 2025).
diabetes (2 papers, 2011 to 2024). "Another study uncovered that iMSC-EVs transferred miR-21-5p and miR-486-5p to promote hippocampal neural stem cells (H-NSCs) proliferation and neurogenesis through inhibiting EphA4, CDKN2C, and FoxO1 expression in diabetes mellitus-postoperative cognitive dysfunction (DM-POCD)." (PMID 39135947, 2024).
epilepsy (2 papers, 2017 to 2024). A brain disorder characterized by episodes of abnormally increased neuronal discharge resulting in transient episodes of sensory or motor neurological dysfunction, or psychic dysfunction. "During the activation, various genes of our predicted EPH family have been identified to promote such biological processes, validating the crucial role of EPH family including our predicted genes EPHA3, EPHA4, EPHA5, EPHA7, and EPHB2 during epilepsy." (PMID 28255556, 2017). "Furthermore, genes such as SCN3B, EPHA4, GABRB3, and SCN2A may play roles in the development of epilepsy in the context of AD." (PMID 38999445, 2024).
infarction (2 papers, 2023 to 2025). A localised pathological necrosis of tissue resulting from obstruction of the blood supply usually by a thrombus, an embolus, or vascular torsion. "Furthermore, the increase in remodeling-related proteins, including EPHA4, PODN, and ALPK3, pointed to favorable structural adaptation following infarction." (PMID 41373456, 2025).
motor neuron disease (2 papers, 2019). "Combined with our previous findings on the role of EphA4 in ALS our current data suggests different contribution for various members of the Eph-ephrin system in the pathophysiology of a motor neuron disease." (PMID 31300041, 2019). "However, our findings in the SMNΔ7 mouse model are in contrast with previous results in the mutant SOD1G93A mouse model for ALS in which similar reduction of EphA4 levels ameliorated motor neuron disease progression." (PMID 31803009, 2019). "Interestingly, knockdown of EphA4 also rescued the axonal deficits in a zebrafish model for SMA, suggesting that the neuroprotective effect of EphA4 inhibition could translate to other motor neuron diseases." (PMID 31803009, 2019).
multiple myeloma (2 papers, 2019 to 2023). "Eph receptor A4 (EphA4) is overexpressed in several tumors and promotes the proliferation of multiple myeloma cells." (PMID 37993880, 2023). "EphA4 binds CDK5 and increases its expression, leading to enhanced AKT activation and cell adhesion-mediated drug resistance in multiple myeloma." (PMID 37993880, 2023).
non-small cell lung carcinoma (2 papers, 2020 to 2021). A group of at least three distinct histological types of lung cancer, including non-small cell squamous cell carcinoma, adenocarcinoma, and large cell carcinoma. "So far, expression of EPHA4 and of some other receptors of EPH family has been used do differentiate between various stages of non-small cell lung carcinoma." (PMID 33322258, 2020).
ovarian carcinoma (2 papers, 2022). A malignant neoplasm originating from the surface ovarian epithelium. "We observed such a situation with the EPHA4 gene, which was expressed below reliable detection levels in all examined ovarian cancer cell lines." (PMID 36362153, 2022).
rectal cancer (2 papers, 2019 to 2021). A primary or metastatic malignant neoplasm that affects the rectum. "Many studies have focused on identifying genes as biomarkers associated with tumor response and survival prognosis of rectal cancer patients with pCRT, such as SERPINB5, CHD4, TCN1, VNN1, EPHA4, PCSK1, and DUOX2 genes." (PMID 33506057, 2021). "Interestingly, overexpression of EphA4 predicts a lesser degree of tumor regression after neoadjuvant chemoradiotherapy in rectal cancer." (PMID 30639848, 2019). "Currently, a lot of previous studies have reported that genes SERPINB5, CHD4, TCN1, VNN1, EPHA4, PCSK1, and DUOX2 as prognostic biomarkers were proven to correlate with poor tumor response and survival prognosis in patients with rectal cancer receiving pCRT." (PMID 33506057, 2021).
scoliosis (2 papers, 2024 to 2025). A congenital or acquired spinal deformity characterized by lateral curvature of the spine. "Our studies using zebrafish have revealed that deficiency of Epha4 can lead to the development of scoliosis." (PMID 40662934, 2025). "To investigate the role of EPHA4 in scoliosis, we utilized zebrafish as a model system due to its versatile nature in modeling adolescent IS." (PMID 40662934, 2025). "Several genes encoding commissural axon guidance molecules, including ROBO3, EPHA4, CHL1, and DSCAM, are strongly associated with scoliosis." (PMID 37962965, 2024). "As scoliosis is not typically associated with Waardenburg syndrome caused solely by PAX3 pathogenic variants, we hypothesize that the deletion of EPHA4 may be responsible for the IS phenotype in this patient." (PMID 40662934, 2025).
sensorineural hearing loss (2 papers, 2025). "In humans, mutations in EphA4 and disruption of ephrin ligand binding are associated with sensorineural hearing loss." (PMID 40463242, 2025).
Sézary syndrome (2 papers, 2015 to 2023). "Several genome-wide transcription profiling studies have demonstrated high EPHA4 expression in Sézary syndrome (SS), a leukemic variant of cutaneous CD4+ T-cell lymphoma (CTCL) with an aggressive clinical course and poor prognosis." (PMID 26376612, 2015). "Since all SS samples tested demonstrated high EPHA4 expression at protein level, this could serve as a novel marker for the diagnosis of Sézary syndrome." (PMID 26376612, 2015). "Besides, EPHA4 may be applied in the molecular diagnosis of Sézary syndrome-related cutaneous T-cell lymphomas, and the membrane-bound EPHA4 receptor can serve as a target for targeted therapeutic interventions." (PMID 37976136, 2023).
tuberculosis (2 papers, 2016 to 2021). A chronic, recurrent infection caused by the bacterium Mycobacterium tuberculosis. "Although the role of EPHA4 has not been explored in malaria, it was proposed as a blood mRNA biomarker for tuberculosis." (PMID 34746025, 2021). "Thus, further studies are needed to assess whether different M. tuberculosis strains, infection sites, previous infections, host genetic background or co-morbidities can affect DOCK9 and EPHA4 mRNA expression profiles." (PMID 27826286, 2016).
viral infection (2 papers, 2016 to 2019). "MAG and EphA4 expression levels were assessed in the crushed sciatic nerve by immunochemistry and Western blotting at 28 days post-viral infection or siRNA interference." (PMID 31798398, 2019). "Interestingly, even though EphA4 was inhibitory for virus infection, it did not seem to be repress syncytia formation, suggesting that EphA4 blocks infection at a step post entry." (PMID 27783670, 2016).
Waardenburg syndrome (2 papers, 2015 to 2025). A disorder characterized by varying degrees of deafness and minor defects in structures arising from neural crest, including pigmentation anomalies of eyes, hair, and skin. "The deletion included the entire PAX3 gene, which was responsible for the Waardenburg syndrome phenotype, and 36 neighboring genes, including EPHA4." (PMID 40662934, 2025). "The rare combination of Waardenburg syndrome phenotype and short stature observed in our patient can be explained by the haploinsufficiency of both PAX3 and EPHA4 genes involved within the deletion." (PMID 25928000, 2015).
aneurysm (1 paper, 2019). Bulging or ballooning in an area of an artery secondary to arterial wall weakening. "We find significant increases in EPHA4 expression concomitant with IL6, CX3CR1, and MCP1 in unruptured and ruptured aneurysms compared to superficial." (PMID 31711546, 2019).
Anxiety (1 paper, 2019). Intense feelings of nervousness, tension, or panic often arise in response to interpersonal stresses. "In constitutive full EphA4-KO mice, cognitive deficits are present which is in contrast to our findings in EphA4flox/flox x Camk2aCre mice which revealed no impairments in activity, anxiety, and spatial and social recognition memory." (PMID 31831046, 2019). "AD mice were more active than Ctrl and EphA4-KO mice with no changes in anxiety." (PMID 31831046, 2019).
brain hemorrhages (1 paper, 2020). "siRNAs against EphA4 have been used to highlight the negative role of EphA4 in recovery after brain hemorrhages while an shRNA against EphA7 was employed to demonstrate its implication in the ovulation process." (PMID 32629797, 2020).
cerebral palsy (1 paper, 2016). A group of disorders affecting the development of movement and posture, often accompanied by disturbances of sensation, perception, cognition, and behavior. "In this way the conditional EphA4 knockout models circuit changes in cerebral palsy." (PMID 27673329, 2016).
craniorachischisis (1 paper, 2017). Craniorachischisis is the most severe form of neural tube defect in which both the brain and spinal cord remain open to varying degrees. "The defect is selective enough not to phenocopy craniorachischisis, yet its caudal and anterior neuropores remain remarkably open in the areas where EphA2 and EphA4 would be expressed in the wildtype." (PMID 29312933, 2017).
distal arthrogryposis (1 paper, 2018). A muscle tissue disease characterized by congenital joint contractures of hand and feet. "Expression of several genes linked to motor neuronopathy and familiar amyotrophic lateral sclerosis (EPHA4, IGHMBP2, VAPB, BICD2, and DYNC1H1) or distal arthrogryposis (MYH8, ZC4H2, MUSK, RAPSN) were significantly upregulated or downregulated." (PMID 29727687, 2018).
Duane retraction syndrome (1 paper, 2019). Duane retraction syndrome (DRS) is a congenital form of strabismus characterized by horizontal eye movement limitation, globe retraction and palpebral fissure narrowing in attempted adduction. "Diseases associated with EPHA4 (Ephrin type-A receptor 4) include lung mucoepidermoid carcinoma and Duane retraction syndrome." (PMID 31117270, 2019).
erythroderma (1 paper, 2015). "Previously, genome-wide mRNA expression profiling studies by us and others have demonstrated that EPHA4 is highly upregulated in SS cells compared to other cutaneous lymphomas, such as mycosis fungoides (MF), benign forms of erythroderma and healthy controls." (PMID 26376612, 2015).
Fibroadenoma (1 paper, 2011). A benign tumor of the breast characterized by the presence of stromal and epithelial elements. "A significantly higher percentage of human invasive ductal carcinoma samples displayed expression of EphA2, EphA4, or EphA7 in tumor epithelium relative to ‘normal’ samples (normal/hyperplastic or fibroadenoma), which were largely negative." (PMID 21935409, 2011).
frontotemporal dementia (1 paper, 2020). Frontotemporal dementia (FTD) comprises a group of neurodegenerative disorders, characterized by progressive changes in behavior, executive dysfunction and language impairment, as a result of degeneration of the medial prefrontal and frontoinsular cortices. "We also included EPHA4, for which only one functional involvement in ALS has been described recently, GRN and MAPT, which are both more likely frontotemporal dementia (FTD)-related genes." (PMID 32987860, 2020).
head and neck cancer (1 paper, 2022). A primary or metastatic malignant neoplasm affecting the head and neck. "Elevated expression of EPHA4 was found in head and neck cancers, although differential outcomes of EphB4-ephrinB2 (its ligand) signaling have been reported in these neoplasms." (PMID 36362284, 2022).
Hyperglycemia (1 paper, 2024). An increased concentration of glucose in the blood. "We tested our proposed mechanism of EphA4 agonism by WCDD301 suppressing glucagon hypersecretion and normalizing hyperglycemia with numerous control experiments." (PMID 38258903, 2024).
idiopathic scoliosis (1 paper, 2025). A scoliosis with no known cause. "Clinical and genetic information on idiopathic scoliosis (IS) patients and functional effect of EPHA4 variants." (PMID 40662934, 2025).
injury (1 paper, 2023). Damage inflicted on the body as the direct or indirect result of an external force, with or without disruption of structural continuity. "Following brain trauma, EphA4 is overexpressed in the damaged cortical tissues, and global deficiency of this receptor demonstrates neuroprotection." (PMID 37941008, 2023).
ischemic stroke (1 paper, 2026). A stroke disorder caused by obstruction of blood flow to the brain, due to thrombotic (local blood clot formation) or embolic (due to a blood clot or other material traveling from another site) event. "Interestingly, 203 upregulated and 212 downregulated genes, including Krt5, Krt14, Col17a1, and Pgam1‐ps1, were shared between EC‐specific KO and Vasculotide‐treated mice, indicating mutual pathways underlying the endothelial EphA4/Tie2 axis following ischemic stroke." (PMID 41164967, 2026). "This work demonstrates that endothelial EphA4 limits Tie2 activation and curbs leptomeningeal collateral expansion after ischemic stroke." (PMID 41164967, 2026). "The opposing roles of EphA4 and Tie2 in collateral dynamics are demonstrated, and a novel molecular program is identified that can be targeted to enhance their diameter enlargement in ischemic stroke." (PMID 41164967, 2026). "To assess whether EC‐specific EphA4 regulates ischemic stroke outcome, we employed EC‐specific knockout mice (EphA4fl/fl/VECadherin‐CreERT2; EC‐specific KO) and wild‐type controls (EphA4fl/fl; WT)." (PMID 41164967, 2026).
memory impairment (1 paper, 2026). "In TBI, EPHA4 leads to abnormal neurogenesis, memory impairment, cerebral cortical injury, and BBB injury." (PMID 41583121, 2026).
metastatic disease (1 paper, 2025). "Finally, we identified the EPHs (EPHA2, EPHA4, EPHA8, and EPHB4) and EFNs (EFNA1, EFNA3, EFNA4, and EFNB2) that are significantly overexpressed in the aggressive epithelioid histological subtype and revealed that the majority of EPHs/EFNs are overexpressed in metastatic disease." (PMID 41516312, 2025).
Obesity (1 paper, 2024). Accumulation of substantial excess body fat. "Therefore, our results suggest that maternal obesity has long-term influence on synaptic plasticity in the hippocampus and impairment of EphA4 signaling is one of the possible mechanisms underlying the abnormal synaptic plasticity." (PMID 38308309, 2024). "Therefore, in this study we determined the impact of maternal obesity in pregnancy on cortical, hippocampal development, vasculature and ephrin-A3/EphA4-signaling, in the adult offspring in mice." (PMID 38308309, 2024). "In contrast to the hippocampus, maternal obesity did not affect mRNA expression of EphA4, PSD-95 and synaptophysin in the PFC (p = 0.479; p = 0.329; p = 0.888; p = 0.535)." (PMID 38308309, 2024).
osteopetrosis (1 paper, 2021). Osteopetrosis, also known as marble bone disease, is a descriptive term that refers to a group of rare, heritable disorders of the skeleton characterized by increased bone density on radiographs. "At seven loci, there was a single putative causal gene: Abca12 at a locus for adult neurogenesis; Epha4 (stress-coping strategy); Pkn2, Slit3, and Pgk1-rs7 (at three different loci for sleep); H60c (home cage activity); and Adcy1 (osteopetrosis)." (PMID 34311762, 2021).
promyelocytic leukemia (1 paper, 2017). "Moreover, EphA2 and EphA4 expression was induced, and ephrin-A4 expression was upregulated, in a human promyelocytic leukemia cell line, HL60, along with monocyte differentiation toward the classical CD14++CD16− monocyte subset." (PMID 28851287, 2017).
Rett syndrome (1 paper, 2022). A severe neurodevelopmental disorder affecting the central nervous system. "Moreover, miR-21-5p from human urine-derived stem cell-derived EVs attenuated Rett syndrome, an early cognitive loss and neurologic deterioration disease, through the inhibition of Eph receptor A4 (Epha4) and its downstream signaling TEX." (PMID 36289747, 2022).
spina bifida (1 paper, 2017). A congenital neural tube defect in which vertebrae are not fully formed. "The Pax3 gene and the EphA4 gene act in concert with each other in causing spina bifida due to interstitial deletion at position 2q36." (PMID 28286691, 2017).
spinal muscular atrophy (1 paper, 2019). A motor neuron disease that affect the muscles, and characterized by muscle weakness and atrophy resulting from progressive degeneration and irreversible loss of the anterior horn cells in the spinal cord (i.e., lower motor neurons) and the brain stem nuclei. "Moreover, loss of EphA4 rescued the motor axon phenotype in a zebrafish model of spinal muscular atrophy (SMA)." (PMID 31803009, 2019).
Splenomegaly (1 paper, 2016). Abnormal increased size of the spleen. "Our study showed similar results that splenomegaly is remarkably associated with the high number of PBL (leukemoid reaction) and the large amount of myeloid progenitor cells in the peripheral blood, which was decreased by EphA4 deleted host." (PMID 26923183, 2016).
thymoma (1 paper, 2021). A neoplasm arising from the epithelial cells of the thymus. "EphA4 and EphA6 displayed higher epithelial expression in thymoma subtypes B2 and B3 as well as thymic cancer compared with subtypes A and AB (p = 0.011 and p < 0.001 for EphA4 and EphA6, respectively)." (PMID 34943502, 2021).
triple-negative breast carcinoma (1 paper, 2022). An invasive breast carcinoma which is negative for expression of estrogen receptor (ER), progesterone receptor (PR), and human epidermal growth factor receptor 2 (HER2). "The current study aims to investigate the clinical significance of EPHA2, EPHA4, and EPHA7 expression in triple-negative breast cancer (TNBC) cases." (PMID 35204461, 2022).